CASR (calcium sensing receptor)
Diseases named in the same sentence as CASR in open-access papers (continued):
Sharing a sentence is not in itself a finding about the gene and the disease.
lymph node metastasis (1 paper, 2018). "Moreover, the decreased CaSR expression correlated with several clinicopathological characteristics, including histologic grade, myometrial invasion and lymph node metastasis but not age and stage." (PMID 29348629, 2018).
male infertility (1 paper, 2020). The inability of the male to effect fertilization of an ovum after a specified period of unprotected intercourse. "Our research enriches knowledge of the role of CaSR in inflammatory diseases and provides new insights into the underlying mechanisms of inflammation-related male infertility." (PMID 33193351, 2020).
medulloblastoma (1 paper, 2016). A malignant, invasive embryonal neoplasm arising from the cerebellum. "Although a role for the CaSR in medulloblastoma has not been established, the identification of key proteins regulating GCP migration and progression is a major goal in medulloblastoma research, and could lead to novel approaches for the development of effective therapeutics." (PMID 27303307, 2016).
metabolic bone disorder (1 paper, 2025). A group of disorders that affect the bones secondary to increased levels of minerals or deficient levels of minerals such as calcium, magnesium, phosphorus, and vitamin D. Representative examples are osteomalacia, osteoporosis, and Paget disease. "An ability to manipulate Pi sensing, akin to what has been done with the calcium sensing receptor, may offer targeted therapies to combat mineralisation defects observed in various metabolic bone disorders." (PMID 40791815, 2025).
myoma (1 paper, 2024). "ANG1, CaSR, and FAK were examined in myoma and peripheral tissue samples taken from women after myoma surgery and in normal uterine muscle tissue samples taken from the control group." (PMID 39000274, 2024). "The CaSR value was reduced in the myoma and peripheral tissue and normal in the group of women without myomas." (PMID 39000274, 2024).
Parkinson’s (1 paper, 2022). "Degenerative diseases of the brain such as Parkinson’s and Alzheimer’s disease may also be affected by both glutathionergics and CaSR in brain tissue; however, their neural and systemic interactions are complex and beyond the scope of the present review." (PMID 35054903, 2022).
Polyuria (1 paper, 2018). An increased rate of urine production. "We thus tested whether the calcium sensing receptor (CaSR) could be triggered by high urinary uric acid levels in the presence of calcium and could mediate polyuria." (PMID 30105595, 2018). "We previously showed in the full body GLUT9 KO mouse model that polyuria was accompanied by urine acidification evoking similar processes found in the hypercalciuric TRPV5 knock-out mice and thought to be mediated by the calcium sensing receptor." (PMID 30105595, 2018).
portal hypertension (1 paper, 2022). Increased blood pressure in the portal venous system. "The correlation between the severity of ACLD and the deficiency of vitamin D could be explained by the fact that vitamin D improves portal hypertension through the activation of Vitamin D receptor (VDR) and Calcium-sensing receptor (CaSR) in a cirrhotic rats model." (PMID 36012285, 2022).
postmenopausal osteoporosis (1 paper, 2024). Metabolic disorder associated with fractures of the femoral neck, vertebrae, and distal forearm. "For instance, strontium ranelate can induce OC-apoptosis through the calcium-sensing receptor and thus be used to treat postmenopausal osteoporosis." (PMID 39200299, 2024).
prostatic (1 paper, 2020). "Different expression levels of both calcium receptors (ranging from 0 to 3 for CaSR and from 0 to 4 for TRPV6) was observed, in particular, in some of the prostatic lesions the expression levels of the two calcium receptors were different." (PMID 32931488, 2020).
rickets (1 paper, 2017). Bone softening and weakening usually caused by deficiency or impaired metabolism of vitamin D. Deficiency of calcium, magnesium, or phosphorus may also cause rickets. "The loss of function of CaSR presents with rickets as the predominant skeletal abnormality in mice, but is rarely reported in humans." (PMID 28690912, 2017). "We did not conduct a functional analysis of the mutant CaSR protein of the patient and could not provide a direct mechanism-based explanation of the relationship between CaSR and rickets." (PMID 28690912, 2017). "We have reported the case of a 16-year-old male with a heterozygous CaSR mutation, who developed skeletal abnormalities of spontaneous fracture with subsequent nonunion, and adolescent rickets." (PMID 28690912, 2017). "We have described a case of FHH with a new heterozygous CaSR mutation, I760N, in a patient who did not exhibit any obvious clinical symptom until the age of 16 years when he developed a spontaneous fracture and adolescent rickets." (PMID 28690912, 2017). "However, rickets and fractures have been rarely described in humans, although they have always been present in CaSR-absent mice." (PMID 28690912, 2017).
scoliosis (1 paper, 2025). A congenital or acquired spinal deformity characterized by lateral curvature of the spine. "Although there have been no reports of patients with FHH3 with scoliosis, mice lacking the CaSR exhibit bone defects and delayed cartilage and growth plate development." (PMID 39949382, 2025).
severe acute respiratory syndrome (1 paper, 2022). A viral respiratory infection caused by the SARS coronavirus. "Given the tight bound between the CaSR, calcium and vitamin D metabolism, we also speculate about their roles in the pathogenesis of severe acute respiratory syndrome coronavirus-19 (SARS-COVID-19) infection and their impact on patients’ prognosis." (PMID 36467702, 2022).
tauopathy (1 paper, 2019). Neurodegenerative disorders involving deposition of abnormal tau protein isoforms (tau proteins) in neurons and glial cells in the brain. "In the tauopathy context, Aβ can bind to the calcium sensing receptor (CaSR) in astrocytes, which triggers signaling pathways involved in the production and release of phosphorylated tau." (PMID 31572186, 2019).
testicular cancer (1 paper, 2020). A primary or metastatic malignant neoplasm that affects the testis. "We previously stated that the CaSR acts as an oncogene in the prostrate, ovarian, and testicular cancer." (PMID 32117726, 2020). "Besides this, the CaSR also acts as an oncogene in several cancers such as ovarian, prostate, and testicular cancer." (PMID 32117726, 2020).
viral infection (1 paper, 2022). "Because viral infection induces inflammatory stimuli, as for the activation of the NLPR3 inflammasome, the pro-inflammatory cytokines could possibly up-regulate parathyroid CaSR expression, as seen for the NLRP3-associated IL1-β cytokine." (PMID 36467702, 2022).
tumor (84 papers, 2008 to 2026). "Our findings further expand our knowledge of the role of the CaSR as a tumour suppressor and the epigenetic mechanisms underlying GEP‐NET biology." (PMID 39579056, 2025). "Although the CaSR plays a critical role in systemic Ca2+ homeostasis and promotes tumor cell growth and migration, the underlying mechanisms remain poorly understood." (PMID 35355564, 2022). "Multivariable logistic regression models were used to analyze the association of CASR SNPs with circulating calcium, parathyroid hormone, vitamin D, and primary and secondary neoplasms." (PMID 34357109, 2021). "Studies have shown that tumor cells with a high expression of CaSR are more susceptible to bone metastasis than tumor cells with a low expression of CaSR." (PMID 32269963, 2020). "Expression of CaSR promotes PTHrP secretion in human BrCa cells and increases osteolytic bone metastases associated with decreased bone formation and increased tumor burden in the mouse intratibial model." (PMID 30151009, 2018). "The number of LCT C and CaSR S risk alleles were associated with increasing tumor incidence (p = 0.035)." (PMID 18980667, 2008). "After genotyping, the relationship between LCT 13910 C/T and CaSR A986S polymorphisms as well as tumor incidence/progression was investigated." (PMID 18980667, 2008). "In addition, a higher expression of the CaSR in CRC tumor tissue was associated with a decreased CRC-specific mortality, but not all-cause mortality." (PMID 39233917, 2024). "Although this suggests the regulation of tumor progression and/or metastasis by high calcium, whether distinct variants of the CaSR mediate the effects of high calcium remains poorly understood." (PMID 34357109, 2021). "Screening of patients for CASR variants at this locus may lead to improved management of high calcium associated tumor progression." (PMID 34357109, 2021). "Using multivariable linear mixed-effects models and adjusting for age and race, we show that circulating calcium levels in BC cases were associated with tumor grade (p = 0.009), clinical stage (p = 0.003) and more importantly, with inactivating mutations of the CASR at the rs1801725 SNP (p = 0.038)." (PMID 28764683, 2017). "However, evidence describing the molecular mechanisms causing the tumor suppressive functions of the colonic CaSR is limited." (PMID 25879211, 2015). "As the CaSR is considered to be a tumor suppressor in the colon, its loss may contribute to the pathogenesis of the disease." (PMID 24691920, 2014). "The number of LCT C and CaSR S risk alleles were correlated with tumor incidence (p = 0.035)." (PMID 18980667, 2008). "However, the true implication of exon 7 CaSR variants in humoral immunity and whether this is associated with tumorigenesis or tumor progression requires further investigations." (PMID 34357109, 2021). "Because continual insertion of CASR into the plasma membrane is required for maintenance of calcium sensitivity, regional aberrant localization patterns suggest disruption of CASR protein movement in a subset of the tumor as a mechanism for the loss of calcium sensing in PHPT." (PMID 27537691, 2016). "Loss or up-regulation of CaSR could result in the development of a neoplastic disease like cancer." (PMID 26010602, 2015). "CaSR plays a crucial role in the development and progression of multiple malignant tumors, with its activation or inhibition influencing tumor cell proliferation, apoptosis, invasion, and metastasis." (PMID 41522513, 2026). "CaSR is therefore a potential anti-tumor target, and CaSR antagonists, as negative regulators, show promise in regulating tumor cell proliferation and invasion." (PMID 41522513, 2026). "This is mediated through the activation of the calcium-sensing receptor (CaSR), which acts as a tumor suppressor in several epithelial tissues." (PMID 41601884, 2026).
tumor (continued). "CaSR can inhibit tumor growth by inhibiting cell proliferation and promoting apoptosis, but it can also promote cell proliferation, invasion and metastasis in some tumors." (PMID 41522513, 2026). "A two-year-old patient with a history of neurofibromatosis type 1 (NF1), NF1 microdeletion and variants of uncertain significance in the CASR, NF2, and POLD1 genes, presented with intestinal subocclusion caused by a 15 cm heterogeneous pelvic tumor." (PMID 40630346, 2025). "Studies have found that signals from the 1,25(OH)2D3 receptor (VDR) and calcium-sensing receptor (CaSR) can inhibit tumor proliferation and metastasis, and promote tumor differentiation and apoptosis." (PMID 39687887, 2024). "CaSR is upregulated in ICC tumor specimens and cell lines, acting as an oncogene to drive ICC progression and poor prognosis." (PMID 39048806, 2024). "RANKL then binds to the RANK receptor and spurs the maturation of osteoclasts, which reabsorb the bone matrix and release the calcium that binds to membrane-bound CaSR on tumor cells." (PMID 38435029, 2023). "Mechanistic studies have suggested that CaSR promotes tumor growth and metastasis through regulating multiply signaling pathways, such as PLC-PKC, MEK-ERK and PI3K-Akt pathways." (PMID 36348350, 2022). "We show that sustained high extracellular Ca2+ decreased the sensitivity of CaSR to Ca2+ but rather stimulated tumor cell growth and migration." (PMID 35355564, 2022). "We show that chronic exposure of TNBC cells to high extracellular Ca2+ led to a decrease in the sensitivity of the CaSR to Ca2+ but rather stimulated tumor cell growth and migration." (PMID 35355564, 2022). "Next, we explored the effect of AC-265347 on CaSR expression levels in the eight tumor samples exposed the longest time to each drug, since we previously observed that CIN-responding tumors were those most exposed to this calcimimetic." (PMID 35457141, 2022). "We show that chronic exposure of TNBC cells to high Ca2+ decreased the sensitivity of CaSR to Ca2+ but stimulated tumor cell growth and migration." (PMID 35355564, 2022). "In 2009, our group described the calcium-sensing receptor (CaSR) as a tumor suppressor gene involved in the differentiation pathways of NB." (PMID 35457141, 2022). "Mechanism studies have found that signals from the 1, 25 (OH)2D3 receptor (VDR) and calcium-sensing receptor (CaSR) can inhibit tumor proliferation and metastasis and promote tumor differentiation and apoptosis." (PMID 36364831, 2022). "As previously reported, the CaSR plays distinct roles in several tissues, including several tumor types." (PMID 34357109, 2021). "Concluding, here we provide preliminary evidence of the involvement of the Hippo pathway in human tumor parathyroid cells and of the existence of a CASR-ROCK-YAP1 axis." (PMID 33670622, 2021). "However, it remains unclear whether single nucleotide polymorphisms (SNPs) that alter the sensitivity of the calcium-sensing receptor (CaSR) to circulating calcium are associated with primary and/or secondary neoplasms at specific pathological sites in patients of European and African ancestry." (PMID 34357109, 2021). "Meanwhile, increasing CaSR activity (cinacalcet group vs. blank control group) resulted in statistical reductions in both tumor volumes and weights (∗p < 0.05)." (PMID 32671062, 2020). "When CasR on the surface of tumor cells is upregulated and activated, it can stimulate PTHrP secretion from tumor cells." (PMID 32269963, 2020). "Identifying the interplay between the CaSR and various factors which aid tumor cell homing, survival and proliferation in the bone microenvironment can shed light on the extent it is involved in the processes." (PMID 32117726, 2020). "When CaSR is upregulated and activated on the surface of tumor cells, it can stimulate the release of PTHrP from tumor cells." (PMID 32269963, 2020).
tumor (continued). "It was reported that high Ca2+ levels which are released during tumor induced bone resorption, and specific CaSR agonists increases ER transcriptional activity and decreases ER protein levels." (PMID 32117726, 2020). "In PCa cell lines, CaSR was reported to be a mediator of Ca2+ effects on cell proliferation and tumor progression." (PMID 32252342, 2020). "In contrast to all of this, and in part due to the growing evidence pointing to a beneficial effect of calcium against colon carcinoma, CasR has been also proposed as a tumor suppressor in this type of cancer." (PMID 33113952, 2020). "The effect of calcium sensing receptor (CaSR) on tumor cell proliferation has been studied in several human cancers, and great discrepancies were found in different tumors." (PMID 32671062, 2020). "It has been suggested that CaSR can act either as a tumor suppressor or as an oncogene, depending on the type of cancer." (PMID 32252342, 2020). "For each model, after the acquisition of the MEMRI experiment, the animals were sacrificed and the tumour cells analyzed for assessing the level of expression of CaSR and TRPV6, respectively." (PMID 32931488, 2020). "Tumor xenograft models also verified the in vivo proliferation-inhibiting role of CaSR by subcutaneous injecting A549 cells into nude mice with or without changes of CaSR activity." (PMID 32671062, 2020). "Many other pathways were described to be downstream targets of CaSR in regulation of tumor cell proliferation." (PMID 32671062, 2020). "Altogether, these evidences confirmed that the CaSR acts as a tumor-suppressor in neuroblastic tumors by promoting tumor differentiation and cell death through ERK1/2 phosphorylation." (PMID 31336912, 2019). "CaSR acts as a tumor suppressor in this tumoral context, and it is downregulated in malignant neuroblastic tumors." (PMID 31293052, 2019). "Mice injected with CaSR-transfected tumor cells showed a higher rate of bone metastases in total as well as an earlier occurrence of metastases compared to mice that were injected with vector-transfected cells." (PMID 29644008, 2018). "Kinase activity of the MAPK, JNK, ERK1/2 and p90RSK as well as the kinase AKT was enhanced after stimulating CaSR-transfected tumor cells with calcium." (PMID 29644008, 2018). "Several studies have demonstrated that CaSR functions as a positive regulator of tumour cell proliferation and migration." (PMID 29348629, 2018). "Numerous studies have indicated that extracellular CaSR plays a critical role in tumour development." (PMID 29348629, 2018). "It is a well-established concept that due to their osteolytic characteristics, RCC bone metastases lead to high calcium levels in serum, potentially inducing enhanced cellular activity of CaSR-expressing tumor cells." (PMID 29644008, 2018). "Immunohistochemistry was performed to determine the quantities and localizations of CaSR, E-cadherin and β-catenin in normal endometrial and tumour specimens." (PMID 29348629, 2018). "High calcium mediated activation of the CaSR not only leads to increased proliferation and migration of BC cells but also increased secretion of tumor cell-derived PTHrP which contributes to the vicious osteolytic cycle)." (PMID 28764683, 2017). "Since CaSR activation on tumor cells promotes the secretion of PTHrP, which is also known to block OPG production, the fact that the neutralizing antibody targeting epiregulin does not totally block CaSR-mediated decrease in OPG expression is not surprising." (PMID 28915604, 2017). "In cancer, CaSR appears to have paradoxical roles, and depending on the tissue involved, it is able to prevent or promote tumour growth." (PMID 28122587, 2017). "An example for the cell-type specific function of CaSR is the contradictory role in cancer development, where it acts as either an oncogene (breast, prostate) or as a tumor suppressor gene (colon, parathyroid)." (PMID 27625611, 2016).